CT83 (cancer/testis antigen 83)
Diseases named in the same sentence as CT83 in open-access papers (continued):
Sharing a sentence is not in itself a finding about the gene and the disease.
cancer (continued). "Shared overexpression was found only for cancer-germline antigens CT83, MAGEA12 and XAGEA1." (PMID 40165973, 2025). "We subsequently asked whether the “HORMAD1 + CT83” signature, as seen in vitro, is germane to the transcriptional profile of cancer cell lines and basal tumors expressing both genes." (PMID 38467851, 2024). "To study whether CT83/TCR1-Ts could recognize the naturally cognate antigen from cancer cell lines, we first checked CT83 and A11 expression in eight cancer cell lines and measured the T-cell response to these cell lines." (PMID 35798537, 2022). "Since the expression of cancer/testis antigens is highly restricted in normal adult tissues and widely distributed in tumor tissues, we examined the expression of CT83 in 120 types of normal human tissues, 33 types of cancer tissues, 1019 cancer cell lines, and 18 types of blood cells." (PMID 34108519, 2021). "By further integrating FUSCC-TNBC, CCLE, TCGA pan-cancer, Expression Atlas, and Human Protein Atlas datasets, we found CT83 is frequently activated in TNBC and many other cancers, while it is always silenced in non-TNBC, 120 types of normal non-testis tissues, and 18 types of blood cells." (PMID 34108519, 2021). "Meanwhile, we also noticed copy number variations and mutations of CT83 are quite rare in any cancer type, and its role in immune infiltration is not significant." (PMID 34108519, 2021). "To investigate whether KK-LC-1 is expressed in other cancer types, we tested 57 cell lines from 10 different types of cancer for CT83 expression by qRT-PCR." (PMID 31455429, 2019). "CT83 had oncogenic functions, including support of growth, survival, and metastasis, and then it could be a useful target for cancer immunotherapy." (PMID 29856138, 2018). "Furthermore, 7G4‐1‐Ga showed greater cytotoxicity to CT83‐expressing human cancer cells in vitro than 1‐Ga." (PMID 29856138, 2018). "Furthermore, 7G4‐1‐Ga showed greater cytotoxicity to CT83‐expressing human cancer cells in vitro than that of 1‐Ga." (PMID 29856138, 2018). "Therefore, we investigated the correlation between the expression level of CT83 mRNA and the copy number status of its DNA to figure out whether the abnormal activation of CT83 in cancer is a consequence of its copy number amplification." (PMID 34108519, 2021). "Thus, CT83 mAb 7G4 might be a good candidate in the development of new targeted PDT for effective treatment of CT83‐expressing cancers." (PMID 29856138, 2018). "CT83/TCR1-Ts demonstrated high avidity recognition and killing in various cancer cell lines in vitro, as well as inhibition of tumor growth in animal models in vivo." (PMID 35798537, 2022). "The core CT genes include CMTM1, CT83 (CXorf61), EZHIP (CXorf67), DCAF4L2, KHDRBS3, LEMD1, PIWIL1, and SPATA6, which contribute to cancer progression and metastasis." (PMID 33426787, 2021). "In summary, we highlighted the significance of CT83 for TNBC and presented a comprehensive bioinformatics strategy for single-gene analysis in cancer." (PMID 34108519, 2021). "In conclusion, we highlighted the significance of CT83 for TNBC and presented a comprehensive bioinformatics strategy for single-gene analysis in cancer." (PMID 34108519, 2021). "Cancer/testis antigens 83 (CT83), also called KK‐LC‐1 or CXorf61, recognized by cytotoxic T lymphocytes (CTL), has become a promising target for immunotherapy." (PMID 29856138, 2018). "Although no direct correlation between CT83 and PD-L1 in immune evasion has been reported, it is evident that both cancer-testis antigens CTAs and PD-L1 play significant roles in enabling tumors to evade the immune system." (PMID 40141328, 2025). "To assess the functional avidity of CT83/TCR1, we performed experiments for T2/A11 stimulation loaded with a titrated concentration of cognate peptides, the recognition of several solid tumor cell lines and the cytotoxicity of three representative cancer cell lines with CT83/TCR1-T cells." (PMID 35798537, 2022).
cancer (continued). "Moreover, based on data from the TISIDB database, the abundance of TILs in pan-cancer tissues is independent of CT83 expression." (PMID 34108519, 2021). "Consistently, we found histone marks associated with promoter activity (H3K27ac, H3K4me3) in sperm and in a basal-like cancer cell line positive for HORMAD1 and CT83 (MDA-MB-436) but not in the normal breast or negative breast cell lines." (PMID 38467851, 2024). "CT83 is frequently overexpressed in TNBC and many cancers but silenced in normal non-testis tissues and blood cells." (PMID 34108519, 2021).
tumor (22 papers, 2014 to 2025). "Furthermore, CT83 OE was associated with increased PD-L1 expression, while CT83 KD resulted in decreased PD-L1 levels, potentially impacting T cell immunity within the tumor microenvironment." (PMID 40141328, 2025). "The immunohistochemical analysis of 60 patient samples revealed CT83 expression in 84.9% of cases, with significant correlations to larger tumor size, elevated squamous cell carcinoma antigen (SCC) levels, and advanced FIGO stages (II–IV)." (PMID 40141328, 2025). "Patients who tested positive for CT83 were significantly more likely to have larger tumor sizes (p = 0.046) and higher serum SCC values (p = 0.037)." (PMID 40141328, 2025). "We investigated CT83 expression and its role in tumor progression and immune evasion using a robust experimental design that included both in vitro experiments and clinical tissue analysis." (PMID 40141328, 2025). "Increasing the resolution of our analysis, we then used full-length scRNA-seq of triple-negative tumors and again identified robust expression of HORMAD1 and CT83 in tumor cells." (PMID 38467851, 2024). "Of the four analyzed triple-negative breast tumors we found several HORMAD1 (in 3/4 tumors) and CT83 (in 4/4 tumors) positive cells: they fall primarily into the tumor cell cluster." (PMID 38467851, 2024). "In the alternative possibility, the expression of HORMAD1 and CT83 occurs after transformation, equipping basal tumor cells with a selective advantage." (PMID 38467851, 2024). "In the present study, KK-LC-1, encoded by CT83, was frequently expressed in non-tumor sites of the GC stomach, but infrequently in those of the non-GC stomach." (PMID 36484013, 2022). "In 17 of 22 (77.3%) patients, CT83 was expressed at either of the two or both of the two non-tumor sites at significantly higher rates than in the remaining GC patients (45.7%, p = 0.0276)." (PMID 36484013, 2022). "In the tumor regression group with 5×106 CT83/TCR1-Ts, dark-stained necrosis of tumor cells was clearly observed in the middle of the T-cell infiltration (photo on the right)." (PMID 35798537, 2022). "In view of the high tumor specificity, pan-cancerous characteristics, and high expression level of CT83, it is worth further studying the antitumor effect of CT83/TCR1-Ts in clinical trials of immunotherapy." (PMID 35798537, 2022). "A higher CT83 expression level indicates a stronger ability of the body to resist tumours and therefore a better prognosis." (PMID 33711953, 2021). "We analyzed the TIMER2.0 and TISIDB database to assess the correlation between the expression of CT83 and the abundance of tumor-infiltrating lymphocytes (TILs)." (PMID 34108519, 2021). "Gene-engineered T cells expressing the KK-LC-1 TCR (KK-LC-1 TCR-Ts) demonstrated recognition of CT83+ tumor lines in vitro and mediated regression of established CT83+ xenograft tumors in immunodeficient mouse models." (PMID 31455429, 2019). "Regarding the top-3 tumor-specific antigens, remaining PPAEs are salivary gland for targeting CT83 and colon for targeting ACTL8." (PMID 31069014, 2019). "We tested if third-party human T cells that were transduced to express the KK-LC-1 TCR (KK-LC-1 TCR-Ts) recognized tumor cell lines that express CT83 and HLA-A*01:01 in vitro." (PMID 31455429, 2019). "The methylation rate of CT83 in tumour tissues was markedly lower than that in the corresponding non‐tumorous tissues." (PMID 30895661, 2019). "The tumor data show a strong correlation between expression and promoter demethylation for CT83." (PMID 38467851, 2024). "Tumor-specific expression of CT83 ensures the safety of T-cell treatment to target this antigen." (PMID 35798537, 2022). "In 69 out of 118 (58.5%) GC patients, CT83 was detected at one or more non-tumor sites." (PMID 36484013, 2022). "Based on our results, CT83 may affect tumor growth, proliferation, and invasion via EMT." (PMID 40141328, 2025). "Additionally, CT83 expression was observed in non-tumor sites of GC patients." (PMID 36484013, 2022).
tumor (continued). "However, when a tumour develops, the CT83 expression level may increase as part of the immune response to the tumour." (PMID 33711953, 2021). "Using the same conditions on 99 tumor sections of mixed types, we verified that most triple-negative tumors (34 out of 40, 85%) expressed HORMAD1 and/or CT83, and this activation is specific to the triple-negative subtype (p-value < 10−4)." (PMID 38467851, 2024). "When the E:T ratio reached 10:1 or higher, most tumor cell lines (BGC823/A11, MB231/A11, and HCC827/A11) were killed by CT83/TCR1-Ts during coculture overnight, among which BGC823/A11 was one of the most sensitive lines." (PMID 35798537, 2022). "CT83 staining was cytoplasmic but similarly marked most tumor cells, and few or no cells of the microenvironment." (PMID 38467851, 2024). "In the present study, we investigated the difference in CT83 expression at non-tumor sites of stomachs with or without tumors." (PMID 36484013, 2022). "CT83 was frequently expressed in non-tumor sites in the GC stomach, but rarely in the non-GC stomach." (PMID 36484013, 2022). "Among the most overexpressed genes in tumor cells compared to normal tissue are genes coding for transcription factors (HOXB9, SIM2, ZIC5, SP8, TFAP2A, FOXE1, HOXB13, and SALL4), cancer testis antigens (CT83), and cytokines activating regulatory Th17 cells (IL23A)." (PMID 37228492, 2023). "All patients with CT83 expression at non-tumor sites of their stomachs without tumors carried Hp." (PMID 36484013, 2022). "Higher CT83 expression in non-tumor sites with GC compared with non-GC stomachs may indicate precancerous levels." (PMID 36484013, 2022).
CT83 also shares sentences with these, for which no sentence is quoted: liver cancer (5 papers); hepatocellular carcinoma (4); adenocarcinoma (2); colorectal cancer (2); non-small cell lung carcinoma (2); pancreas cancer (2); stomach cancer (2); adenoma (1); bladder cancer (1); chondrosarcoma (1); endometrioid adenocarcinoma (1); esophageal carcinoma (1); esophageal squamous cell carcinoma (1); head and neck cancer (1); infection (1); invasive ductal carcinoma (1); leiomyosarcoma (1); liposarcoma (1); lung squamous cell carcinoma (1); lymph node metastasis (1); nasopharyngeal carcinoma (1); osteosarcoma (1); pancreatic cancer (1); phyllodes tumor (1); rectum adenocarcinoma (1); sarcoma (1); soft tissue sarcoma (1); squamous cell carcinoma (1); stomach adenocarcinoma (1); testicular cancer (1).
A further 2 diseases each share a sentence with CT83 in 1 paper.